MYH11 (myosin heavy chain 11)
Diseases named in the same sentence as MYH11 in open-access papers (continued):
Sharing a sentence is not in itself a finding about the gene and the disease.
Alzheimer disease (3 papers, 2022 to 2024). A progressive, neurodegenerative disease characterized by loss of function and death of nerve cells in several areas of the brain leading to loss of cognitive function such as memory and language. "Multiethnic studies identified ten genes including MYH11 are differentially expressed in the context of Alzheimer’s disease (AD)." (PMID 36506317, 2022). "By utilizing the ROC curve to assess the prognostic value of hub genes in the PPI network, 3 out of 5 shared hub genes, namely, CXCR4, MYH11, and TGFB1, showed potential indications as potential biomarkers for Alzheimer’s disease." (PMID 37705610, 2023).
Arterial stenosis (3 papers, 2022 to 2024). Narrowing or constriction of the inner surface (lumen) of an artery. "As in previous experiments, confocal microscopy showed that in control Myh11CreERT2 x Raptor+/+xR26eYFP mice (where raptor was intact), Myh11 + /eYFP+ cells robustly infiltrated the coronary artery intima following CAWS injection, causing profound arterial stenosis." (PMID 39271773, 2024).
cardiac hypertrophy (3 papers, 2020 to 2025). "Given that MYH11 is selectively expressed in SMCs, these results implicate a role of SMCs in the arteries of the heart contributing to cardiac hypertrophy and failure with pressure overload." (PMID 40658722, 2025). "Given that MYH11 is selectively expressed in SMCs, these results implicate a role of vascular SMCs in the heart contributing to cardiac hypertrophy and failure with pressure overload." (PMID 39185210, 2024). "Thus, MYH11 rare variants may trigger excessive SMC IGF-1 production and be the source of SMC-to-cardiomyocyte signaling to drive cardiac hypertrophy and failure in Myh11E1892D/E1892D mice after TAC." (PMID 39185210, 2024).
cardiomyopathy (3 papers, 2020 to 2022). A disease of the heart muscle or myocardium proper. "Therefore, it was speculated that TPM1, MYL2 and MYH11 could be the targets of obesity-induced cardiomyopathy, thus providing a theoretical basis for future drug development." (PMID 33785854, 2021). "Among the identified DEGs, IGF1, MYH11, and TGFB3 had a high degree of interaction in the PPI network and were predicted to be key genes in cardiomyopathy." (PMID 35845066, 2022). "The CTD database showed that the common hub genes (IGF1, MYH11, TGFB3, ALB, and AGT) were targets in cardiomyopathies." (PMID 35845066, 2022). "Secondly, the in-depth mechanism of TPM1, MYL2 and MYH11 protein changes in obese cardiomyopathy has not been studied." (PMID 33785854, 2021).
colon cancer (3 papers, 2017 to 2021). "Compared to adjacent normal colon, upregulation of Defa6 and Bcl3 and downregulation of App, Myh11, and Myl9 indicated changes in tight junctions and anti-microbial activity in Pirc colon tumors." (PMID 34494932, 2021). "In addition, we also analyzed a pair of genes, LIMS2, down-regulated in colon cancer epithelial cells compared with normal epithelial colon cells, and MYH11 significantly up-regulated in colorectal tumor tissues compared with normal colon tissues." (PMID 28427173, 2017).
colorectal tumor (3 papers, 2008 to 2023). "Studies have reported somatic mutations and heterogeneity of the MYH11 gene in gastric and colorectal tumours." (PMID 37189448, 2023).
coronary atherosclerosis (3 papers, 2016 to 2023). Atherosclerosis of the coronary vasculature. "Low expression of MYH11 can promote coronary atherosclerosis and destroy the stability of coronary artery walls, thereby causing coronary artery dysfunction, reducing blood perfusion of myocardial cells, and aggravating the hypoxic damage of myocardial cells." (PMID 33785854, 2021).
familial thoracic aortic aneurysm and dissection (3 papers, 2022 to 2024). "Several genetic defects, including a mutation in myosin heavy chain 11 (Myh11), are reported to cause familial thoracic aortic aneurysm and dissection (FTAAD)." (PMID 37894894, 2023). "Pathogenic variants in myosin heavy chain (Myh11) cause familial thoracic aortic aneurysms and dissections (FTAAD)." (PMID 35614093, 2022).
Obesity (3 papers, 2021 to 2025). Accumulation of substantial excess body fat. "Our lab is currently seeking answers to these important questions, in the context of obesity and metabolic syndrome, in PAI-1fx/fx mice crossed to Lyve1, Prox1, or Myh11 Cre-lines." (PMID 35308249, 2022).
schizophrenia (3 papers, 2009 to 2024). A major psychotic disorder characterized by abnormalities in the perception or expression of reality. "Chromosome 16p13.3 duplication including MYH11 gene—chromosomal deletions or reciprocal duplications of the 16p13.1 region have been linked to several neuropsychiatric conditions such as autism, schizophrenia, epilepsy, and attention-deficit/hyperactivity disorder (ADHD)." (PMID 37443678, 2023). "All three deletions included the region chr16:15387380–16198600 (and the genes MPV17L, c16orf45, KIAA0430, NDE1, MYH11, KIAA0866, c16orf63, ABCC1 and MRP6/AbCC6) indicating that a large deletion of this region may be a recurrent schizophrenia risk factor." (PMID 19197363, 2009).
acute leukemia (2 papers, 2021 to 2023). A clonal (malignant) hematopoietic disorder with an acute onset, affecting the bone marrow and the peripheral blood. "Fusion genes have been identified as specific molecular markers of acute leukemia, and PTPN11 mutations have been observed to co-exist with MLL-AML (MLL-AF6, MLL-AF10) and CBFβ-MYH11, which is in accordance with previously reported findings in the literature." (PMID 38025540, 2023).
Aortic root aneurysm (2 papers, 2024 to 2025). An abnormal localized widening (dilatation) of the aortic root. "A heterozygous missense VUS in the coiled-coil domain of MYH11, p.Glu1892Asp, was identified in a proband with aortic root aneurysm." (PMID 40658722, 2025). "A missense VUS in the coiled-coil domain of MYH11, p.Glu1892Asp, was identified in a proband with aortic root aneurysm." (PMID 39185210, 2024).
arterial disease (2 papers, 2018 to 2022). "The aberrant methylation in the promoter region of MYH11 and CNN1 genes, two hyper-down hub genes screened in our study, was found to be associated with VSMCs differentiation in arterial disease." (PMID 36292702, 2022).
endometrial cancer (2 papers, 2024 to 2025). Primary or metastatic malignant neoplasm involving the endometrium (mucous membrane that lines the endometrial cavity). "In endometrial cancer, a spatially separated vascular CAFs subgroup characterized by high levels of MYH11, ESAM, MCAM, and EPAS1 was a poor prognostic factor for patients with endometrial cancer." (PMID 39764562, 2025).
endometriosis (2 papers, 2021 to 2024). The growth of functional endometrial tissue in anatomic sites outside the uterine body. "In addition, some identified hub genes of the EC (TAGLN, GATA6, CDH3, CLU, COL8A1, MYH11, MYOCD) and EU (CXCL13, DDK-1, KLF4, CYP2E1, CYP4B1 and PROK1) have been reported be associated with endometriosis." (PMID 34522169, 2021).
fibrosis (2 papers, 2025). the formation of excess fibrous connective tissue in an organ or tissue in a reparative or reactive process. "Moreover, the roles of endothelial cells, MYH11_myoCAF, SPP1_Macro and MKI67_Macro became more pronounced, indicating a more intricate network of cellular interactions within the TME of the Fibrosis+ LM." (PMID 41258075, 2025).
gastroparesis (2 papers, 2016 to 2019). Paralysis of the muscles of the stomach wall resulting in delayed emptying of the gastric contents into the small intestine. "The MYH11 variants could also predispose individuals to stress-induced changes in contractile function that could contribute to the development of poorly understood motility disorders that are exacerbated by inflammatory states, such as irritable bowel syndrome and gastroparesis." (PMID 26893369, 2016).
lymph node metastases (2 papers, 2021 to 2022). "By analyzing the clinicopathologic parameters of the patients, we observed that the poor expression of MYH11 also correlated with the tumor size, TNM stage, and lymph node metastasis of the patients." (PMID 34380460, 2021). "In this study, a relationship was substantiated between MYH11 downregulation and the hypermethylation of its promoter in GC, and poorly expressed MYH11 was correlated with a poor prognosis and was intimately intertwined with tumor size, TNM stage, and lymph node metastasis of GC patients." (PMID 34380460, 2021).
multisystemic smooth muscle dysfunction syndrome (2 papers, 2021 to 2024). A spectrum of conditions caused by monoallelic pathogenic variants in ACTA2. "This functional relationship explains the phenotypic similarities between Multisystemic Smooth Muscle Dysfunction Syndrome caused by ACTA2 mutations, and Megacystis-Microcolon-Intestinal Hypoperistalsis Syndrome 2 caused by MYH11 mutations." (PMID 39480826, 2024). "The gene ontologies for list 5+ linked FOXF1, KCNMB1, MYH11, and PLN to Multisystemic Smooth Muscle Dysfunction Syndrome." (PMID 39480826, 2024). "We propose that FOXF1, KCNMB1, and MYH11 are novel genes in Multisystemic Smooth Muscle Dysfunction Syndrome." (PMID 39480826, 2024).
thyroid carcinoma (2 papers, 2020 to 2021). "In TC, among those over-expressed in males, we found PPARG, previously reported in thyroid carcinomas, ERCC5, MYH11, LEMD2, ZNF133, and IDH1, the latter found to be mutated in thyroid carcinomas." (PMID 32849808, 2020).
acute monocytic leukemia (1 paper, 2024). Acute monoblastic leukemia (AML-M5), is one of the most common subtypes of acute myeloid leukemia (AML) that is either comprised of more than 80% of monoblasts (AML-M5a) or 30-80% monoblasts with (pro)monocytic differentiation (AML-M5b). "P1 was also significantly enriched in WHO subtype AML with KMT2A rearrangement (q < 0.05), acute monocytic leukemia, and AML with CBFB::MYH11 fusion." (PMID 38724673, 2024).
adenoma (1 paper, 2008). A neoplasm arising from the epithelium. "To establish the contribution, timing and frequency of the MYH11 frameshift mutation in HNPCC tumorigenesis, we analysed a series of adenomas and cancers from HNPCC patients." (PMID 18941465, 2008).
arachnodactyly (1 paper, 2019). "In particular, aortic ectasia resulted significantly influenced by FBN1 rare pathogenic variants and by FBN1, COL1A1 and COL3A1 VUS, arachnodactyly resulted influenced by FBN1 rare pathogenic and VUS rare variant; MYH11 pathogenic variants and FBN1 VUS resulted associated with ectopia lentis." (PMID 31536524, 2019).
ascending aortic aneurysm (1 paper, 2017). "Through the use of iPSCs modeling the BAV/TAA, we found that the defective differentiation of SMCs from neural crest stem cells, modeling the root, and ascending aortic aneurysm, manifested as decreased expression of MYH11 and contractile function of SMCs." (PMID 28659818, 2017).
autosomal dominant cutis laxa (1 paper, 2024). Autosomal dominant cutis laxa (ADCL) is a connective tissue disorder characterized by wrinkled, redundant and sagging inelastic skin associated in some cases with internal organ involvement. "MYH11 and SYNPO2 linked to EMILIN1-related Connective Tissue Disease, AOC3 and MYH11 linked to Autosomal Dominant Cutis Laxa, MYH11 and SYNPO2 linked to Lethal Arteriopathy Syndrome due to Fibulin-4 Deficiency, while AOC3 and TAGLN linked to Renal Tubular Dysgenesis of Genetic Origin." (PMID 39480826, 2024). "We propose that AOC3 and MYH11 are novel genes in Autosomal Dominant Cutis Laxa." (PMID 39480826, 2024).
Berdon's syndrome (1 paper, 2021). "The mutation of the following genes: MYH11, MYLK, LMOD1, and MYL9, is also involved in the pathogenesis of Berdon's syndrome in individual cases." (PMID 33859849, 2021).
brain infarcts (1 paper, 2025). "We report a case of a rare heterozygous MYH11:c.3818G>T, p.(Arg1273Leu) missense variant in a patient with severe cerebral arterial and aortic pathology and clinical and radiological brain infarcts." (PMID 41040781, 2025).
carotid atherosclerosis (1 paper, 2018). A thickening and loss of elasticity of the walls of carotid arteries that occur with formation of atherosclerotic plaques. "Additionally, MYH11, KLF5, and SPP1 expression patterns were found to be associated with symptomatology of human carotid atherosclerosis." (PMID 29562638, 2018).
cervical cancer (1 paper, 2025). A primary or metastatic malignant neoplasm involving the cervix. "Multiplex immunofluorescence and immunohistochemical analyses were performed on both cultured cells and human cervical cancer tissue samples to characterize the spatial distribution and dynamic remodeling of MYH11 during stromal reorganization." (PMID 40616092, 2025). "To further elucidate the functional characteristics of C0 MYH11 + CAF, we co-cultured isolated C0 MYH11 + CAF with high- and low-invasive cervical cancer cells." (PMID 40616092, 2025).
cholangiocarcinoma (1 paper, 2024). A carcinoma that arises from the intrahepatic biliary tree (intrahepatic cholangiocarcinoma) or from the junction, or adjacent to the junction, of the right and left hepatic ducts (hilar cholangiocarcinoma). "Fib-C3 cells were like the vascular cancer-associated fibroblasts (vCAFs) in the intrahepatic cholangiocarcinoma and exhibited high expression levels of ACTA2, RGS5, MYH11, and EPAS1." (PMID 39107908, 2024).
chronic kidney disease (1 paper, 2016). Impairment of the renal function secondary to chronic kidney damage persisting for three or more months. "Changes of Myh 6, Myh7 and Myh11 phosphorylation suggest that dysregulation of cytokinesis may be associated with salt sensitivity in chronic kidney disease." (PMID 27775022, 2016).
colon adenocarcinoma (1 paper, 2021). "MYH11 positively modulated the immune-related gene GLP2R in colon adenocarcinoma." (PMID 34109184, 2021).
congenital glaucoma (1 paper, 2024). "The gene ontologies for list 7+ linked the non-overlapping genes CDC42EP2, CLDN5, CNN1, DES, KCNMB1, and MYH11 to Congenital Glaucoma." (PMID 39480826, 2024).
differentiated thyroid carcinoma (1 paper, 2021). Differentiated thyroid carcinoma (DTC), also known as papillary or follicular thyroid carcinoma, is a slow-growing malignancy usually presenting in adults as an asymptomatic thyroid mass. "It has been reported that a risk factor for differentiated thyroid carcinoma is GD, suggesting that the level of MYH11 may be a prognostic marker for TAO." (PMID 33934566, 2021).
distal hereditary motor neuropathy type 2 (1 paper, 2024). "KCNMB1, MYH11, PNPLA2, and TAGLN linked to Distal Hereditary Motor Neuropathy type 2." (PMID 39480826, 2024). "We propose that KCNMB1, MYH11, TAGLN, and PNPLA2 are novel genes in Distal Hereditary Motor Neuropathy type 2." (PMID 39480826, 2024).
dysplasia (1 paper, 2011). A usually neoplastic transformation of the cell, associated with altered architectural tissue patterns. "Fibromuscular dysplasia was evident in arteries of the vasa vasorum, a finding previously observed in aortas from patients with MYH11 mutations." (PMID 21698135, 2011).
E. coli infection (1 paper, 2023). "In addition, MYH11, as top DE gene, was enriched in tight junction pathway, which acts as an intestinal barrier in E. coli infection." (PMID 37085748, 2023).
head and neck cancer (1 paper, 2020). A primary or metastatic malignant neoplasm affecting the head and neck. "Myosin MYH11 were previously found to be associated with variety of cancers, such as oral squamous cell carcinoma, meanwhile, a recent study has described MYH11 as a potential biomarker and candidate drug target for head and neck cancer management." (PMID 32597160, 2020).
head and neck squamous cell carcinoma (1 paper, 2025). A squamous cell carcinoma that arises from any of the following anatomic sites: lip and oral cavity, nasal cavity, paranasal sinuses, pharynx, larynx, and salivary glands. "MYH11 is also a prognostic gene in head and neck squamous cell carcinoma, with significantly reduced infiltration of CD8 + T cells, B cells, neutrophils, and NK cells in high-risk groups." (PMID 40616092, 2025).
Holt-Oram syndrome (1 paper, 2024). Holt-Oram syndrome (HOS) is the most common form of heart-hand syndrome and is characterized by skeletal abnormalities of the upper limbs and mild-to-severe congenital cardiac defects. "The gene ontologies for list 4+ linked FOXF1, MYH11, and TAGLN to Holt-Oram Syndrome." (PMID 39480826, 2024). "We propose that FOXF1, MYH11, and TAGLN are novel genes in Holt-Oram Syndrome." (PMID 39480826, 2024).
Hyperglycemia (1 paper, 2023). An increased concentration of glucose in the blood. "Further, real-time PCR demonstrated a statistically significant increase in Myh11 mRNA expression in smOGTKO vs. smOGTWT mice in response to STZ-induced hyperglycemia (p < 0.05)." (PMID 37175604, 2023).
hypopharyngeal cancer (1 paper, 2023). Carcinoma, predominantly squamous cell, arising from the epithelial cells of the hypopharynx. "In our research, we found that MYH11 mutated in 7 patients, and we found two pathogenic or possibly pathogenic mutations (rs375159635, rs751495086), which may be related to the pathogenesis of hypopharyngeal cancer." (PMID 36596842, 2023). "However, the relationship between MYH11 and hypopharyngeal cancer has not yet been reported." (PMID 36596842, 2023).
ileus (1 paper, 2025). Decrease in peristalsis in the absence of a mechanical bowel obstruction. "Both patients with MYH11 variants were female and showed an unfavorable outcome with PN dependency and decompression ostomy due to recurrent ileus episodes." (PMID 41387873, 2025).
infertile (1 paper, 2025). "The loss of contractile markers, such as MYH11 and α-SMA, is notable as similar alterations have been observed in infertile patients." (PMID 41348959, 2025).
Insulin resistance (1 paper, 2021). Increased resistance towards insulin, that is, diminished effectiveness of insulin in reducing blood glucose levels. "The CD36, GLUL, MYH11, CD163, and COL4A2 genes were closely associated with weight loss, while the ACACB gene was closely related to insulin resistance." (PMID 34085602, 2021).
keloid (1 paper, 2007). An irregularly shaped, elevated mark on the skin caused by deposits of excessive amounts of collagen during wound healing. "Elevated expression of DES, MYH11, MYL9 and SMTN in leiomyomas and several KRTs in keloids and scars reflects the cellular composition of these tissues." (PMID 17718906, 2007).
kidney damage (1 paper, 2016). "The most linked proteins included Myh6, Myh7, Myh11, Lmna, Des, Tnni3, Mydpc3 and Vcl, revealing that these molecules may be important targets of signaling pathways involved in salt sensitivity in advanced kidney damage." (PMID 27775022, 2016).
laryngeal carcinoma (1 paper, 2023). Carcinoma that arises from the laryngeal epithelium. "At present, our results suggest that the expression of POLR2J3 and MYH11 genes is associated with the prognosis of laryngeal cancer patients." (PMID 37598251, 2023). "Compared with adjacent tissues, POLR2J3 protein and MYH11 protein were significantly overexpressed in laryngeal cancer tissues." (PMID 37598251, 2023).
lung fibrosis (1 paper, 2023). "In addition, CC-11050 treatment significantly downregulated the expression of genes that play a key role in lung fibrosis, such as TGFB1 (16 dpi; p=0.0433), COL1A1 (16 dpi, p=0.009), TAGLN (16 dpi; p=0.0218), MYH11 (4 dpi; p=0.0042; 16 dpi; p=0.05) and SMAD2 (16 dpi; p=0.008)." (PMID 37854602, 2023).
neurofibromatosis type 1 (1 paper, 2026). A clinically heterogeneous, neurocutaneous genetic disorder characterized by cafe-au-lait spots, iris Lisch nodules, axillary and inguinal freckling, and multiple neurofibromas. "We analyze the role of genes involved in vascular smooth muscle cell contractility (ACTA2, MYH11), TGF-β signaling, and DNA repair mechanisms that drive MMS, alongside the genetic basis of syndromic forms associated with neurofibromatosis type 1, trisomy 21, and RASopathies." (PMID 42196405, 2026).